HAS2 (hyaluronan synthase 2)
Diseases named in the same sentence as HAS2 in open-access papers (continued):
Sharing a sentence is not in itself a finding about the gene and the disease.
tumor (continued). "Hence, we correlated the expression level of the tumor-upregulated gene signature, comprising HAS2, MMP9, CXCL8, CXCL11, IL1B, and IL6, with the ratio of infiltrating M1 macrophages." (PMID 38329386, 2024). "In breast cancer, both high HAS2 and HA levels have been shown to induce the recruitment of tumor-associated macrophages (TAM) and tumor neovascularization; stromal HA, via macrophage recruitment, remodels the local microenvironment to promote the formation of tumor vasculatures." (PMID 37568628, 2023). "Therefore, targeting the reduction in HAS2 expression or decreasing the accumulation of HA has been shown to enhance immune cell infiltration and improve anti-tumor immunity in preclinical models." (PMID 37636435, 2023). "Mechanistically, MFAP5 deficiency in CAFs downregulates HAS2 and CXCL10 via MFAP5/RCN2/ERK/STAT1 axis, leading to angiogenesis, hyaluronic acid (HA) and collagens deposition reduction, cytotoxic T cells infiltration, and tumor cells apoptosis." (PMID 37156839, 2023). "We could previously show a significant association between the expression of the synthase HAS2 and the hyaluronidase HYAL1 in the primary tumor of BC patients and the development of BM." (PMID 36291142, 2022). "HAS2 has been shown to control tumor development and cell aggressiveness in many studies." (PMID 36613567, 2022). "We could show that HAS2 expression correlates with higher tumour cell growth and viability and lower patients’ survival." (PMID 35767191, 2022). "We hypothesized that the expression of HAS2 could have an effect on the success of therapy and sphere formation capability and cohesion of the tumour cells." (PMID 35767191, 2022). "Finally, recent data demonstrated that tumor-associated mesenchymal stem-like cells secreted C5a, which activates ERK and triggers expression of the HA synthase HAS2, contributing to HA abundance and enhancing GBM invasiveness in a nude mice model." (PMID 33744285, 2021). "We showed that KLF7 overexpressing accelerated xenograted tumor development of Hec-1-B cells, which could be reversed by HAS2 knockdown." (PMID 33892667, 2021). "These discoveries raised the interesting possibility that SPHK1 and HAS2 might play important roles in tumor progression." (PMID 33506044, 2021). "Lastly, we explored whether KLF7/HAS2 cascade promoted xenograted tumor development by implanting equal number of Hec-1-B cells expressing Ctrl, KLF7 overexpressing, and KLF7 overexpressing plus shHAS2 lentiviruis onto female nude mice." (PMID 33892667, 2021). "HAS2 has been demonstrated to promote tumor progression in some cancers." (PMID 32862195, 2021). "And HAS2 was found mainly localized to the nuclear speckles, which suggests HAS2 may be involved in tumor proliferation." (PMID 34093817, 2021). "Mechanistically, tranilast facilitated ECM remodeling by reducing TGFβ1 expression, thereby inhibiting Smad2/3 phosphorylation, and suppressing TGFβ-mediated expression of COL1A1, connective tissue growth factor (CTGF), and hyaluronan synthase 2 (HAS2) in MCF10CA1a tumor xenografts." (PMID 33391538, 2021). "The ceRNA network and the hsa_circ_0002951/hsa-miR-548k/HAS2 pathway constructed based on pRS may help in revealing the tumor lethal mechanism." (PMID 34093817, 2021). "Unexpectedly, HAS2 overexpression in GBM cells abolished tumor formation in the brain in a mouse model; the authors proposed that this was due to a lack of HYAL activity, suggesting that gliomas may be more aggressive when coexpressing HAS and HYALs." (PMID 33744285, 2021). "Increased expression of hyaluronan synthase 2 (HAS2) in metastatic tumor cells is crucial for the interaction of tumor cells and macrophages in bone, this interaction increases PDGF secretion in macrophages, which promoted stromal cells activity and cancer cell self-renewal." (PMID 32326073, 2020).
tumor (continued). "In addition, research has proposed that HAS2 affects hyaluronic acid synthesis as a result of HA/CD44 signaling pathway activation to influence tumor microenvironment transformation." (PMID 31109321, 2019). "We demonstrated that TGIF1 inactivation promotes KrasG12D-driven pancreatic tumorigenesis and that TGIF1 ablation has tumor-promoting effects and activates the HAS2/CD44 cancer stemness pathway, a potent regulator in the induction of TAM polarization, which enhances PDAC distant metastasis." (PMID 31109321, 2019). "Deciphering the molecular mechanisms highlighted the TGIF1 loss-induced activation of the hyaluronan synthase 2 (HAS2)-CD44 signaling pathway and upregulation of the immune checkpoint regulator PD-L1 to facilitate the epithelial–mesenchymal transition (EMT) and tumor immune suppression." (PMID 31109321, 2019). "However, co-expression of HYAL1 and HAS2 restored the growth of tumor cells to the same level as control cells." (PMID 29914429, 2018). "The secondary objective was to lend credence to the hypothesis that AGL affects tumor biology by HAS2 mediated HA synthesis." (PMID 29682180, 2018). "Increased intensities of HAS2 and HYAL2 were associated with increased tumor cell proliferation." (PMID 29914429, 2018). "However, an HA-independent function of HAS2 supporting tumor progression was suggested by recent findings." (PMID 28086235, 2017). "We wanted to understand whether EMT marker expression and HAS2 were correlated in cell lines and tumor samples." (PMID 28086235, 2017). "Here we analyzed whether tumor cell secreted HA and HAS2 expression is promoting ZEB1-dependent EMT and found that HA in combination with CD44s activates ZEB1 expression." (PMID 28086235, 2017). "HAS2 is involved in tumor progression and acts in concert with ZEB1-driven EMT." (PMID 28086235, 2017). "HAS2 expression was positively correlated with that of α-SMA in the tumor stroma, which implied that CAFs might be the main source of HAS2 in the tumor stroma of the OSCC." (PMID 27884164, 2016). "Interestingly, a previous study demonstrated that HAS2 mRNA expression is significantly increased in PDAC cells in response to co-culture with tumor-derived stromal fibroblasts." (PMID 26684359, 2016). "The secondary objective was to lead credence to the hypothesis that AGL affects tumor biology by RHAMM downstream of HAS2/HA axis as well as other effectors such as SHMT2." (PMID 27595989, 2016). "Moreover, expression levels of stromal HAS1 and HAS2 during breast tumour are related to obesity, large tumor size, lymph node positivity, and estrogen receptor negativity." (PMID 25126569, 2014). "However, it is of high importance also to consider the role of HAS2 and the synthesis of hyaluronan by stromal fibroblasts in tumour malignancies." (PMID 25126569, 2014). "Furthermore, mRNA expression of HAS1 and HAS2 were significantly upregulated in muscle-invasive tumor stages (pT2, pT3 and pT4)." (PMID 24069434, 2013). "In addition to samples with weakly stained epithelial tissue similar to normal ovaries, 64% of tumor samples showed a more intense epithelial HAS2-immunostaining." (PMID 19435493, 2009). "Moreover, due to its inhibitory effect on HAS2/3, 4-MU may be more advantageous in treating tumor-fibrosis co-morbidities than FAS inhibitors alone, such as TVB-2640." (PMID 40839202, 2025). "Finally, we preliminarily validated the impact of HAS2 on tumor development in GBM cell lines." (PMID 37636435, 2023). "Increased HAS2 activity may contribute to tumor-promoting effects by encouraging inflammation." (PMID 36613567, 2022). "Therefore, KLF7 upregulation of HAS2 contributes to UCEC tumor growth." (PMID 33892667, 2021). "Thus, we consider that dual targeting of NRG1 and HAS2 may be an interesting treatment strategy applicable for tumours with high expression of NRG1." (PMID 33692466, 2021).
tumor (continued). "Downregulation of HAS2 expression resulted in an inhibition of tumor cell growth and migration as well as an enhancement of cisplatin sensitivity, suggesting the importance of tumor cell HA production to promote in vitro tumor progression behaviors in oral cancer cells." (PMID 28837080, 2017). "However, it is still largely unknown whether there is a correlation between the HAS2 expression levels in CAFs and tumor aggressiveness." (PMID 27884164, 2016). "Indeed, the important role of stroma-derived hyaluronan on tumor vascularization was demonstrated when the implantation of HAS2 null fibroblasts with epithelial tumor cells into nude mice resulted in attenuated tumor angiogenesis and lymphangiogenesis with impaired macrophage activation." (PMID 24083250, 2013). "In univariate analysis HA, HAS-2, HYAL-1, Slug, MMP-9, and N-Cadh staining in tumor tissues significantly correlated with metastasis (p ≤ 0.002 in each case)." (PMID 40149256, 2025). "As an extracellular matrix component, while HA was localized in the stromal compartment, HAS-2, HYAL-1, Slug, MMP-9, and N-Cadh were expressed in tumor cells." (PMID 40149256, 2025). "Mechanistic investigations demonstrate that cytosolic KIAA1429 interacts with IGF2BP3 to stabilize m6A-hypermethylated hyaluronan synthase 2 (HAS2) mRNA, thereby promoting oncogenic hyaluronan synthesis and tumor growth." (PMID 40986143, 2025). "In this model, overexpression of HYAL1—either alone or in combination with hyaluronan synthase isoforms HAS2 or HAS3—was found to accelerate HA turnover, thereby increasing the frequency of tumor development and metastasis." (PMID 41421148, 2025). "HA production was also evaluated by immunohistochemistry analysis of HAS1, HAS2, HAS3, HYAL1, and HYAL2 expression on tumor cells." (PMID 39858106, 2025). "These compounds likely reduce low-molecular-weight HA production through coordinated regulation of HAS2 and HYAL1 expression, thereby attenuating HA-CD44 signaling pathway activity and ultimately inhibiting tumor growth." (PMID 41421148, 2025). "Conversely, a set of genes, namely CLIP4, HAS2, and KCTD12 (p < 0.01), were found to be notably downregulated in tumor cells." (PMID 38549669, 2024). "We first analyzed HA synthases HAS1, HAS2, and HAS3, hyaluronidases HYAL1 and HYAL2, ABCC5 transporter, and CD44 expression in tumor tissue (TT) in TCGA database." (PMID 39039104, 2024). "An interesting study highlighted the strict correlation between HAS2 expression, HA/CD44 signaling, and ER-dependent tumor aggressiveness." (PMID 37568628, 2023). "HAS2 and CD44 are known to be highly expressed in ER− breast cancer, promoting tumor aggressiveness." (PMID 37568628, 2023). "In contrast, the expression of HAS2 (fold change = 1.42), HYAL2 (fold change = 1.84) and HYAL3 (fold change = 1.94) was significantly increased in the tumour tissue." (PMID 35767191, 2022). "Lastly, knockdown of HAS2 reversed the oncogenic role of KLF7 on UCEC cell proliferation, migration, and xenografted tumor development." (PMID 33892667, 2021). "On the other hand, several members of the HA signaling pathway, like HA synthases (HAS1, HAS2, HAS3), HA receptors and hyaluronidases (mainly HYAL1) are critical determinants of growth and progression of the tumor." (PMID 32610620, 2020). "It is well known that members of the family of molecules of the HA signaling pathway, like HA synthases (HAS1, HAS2, HAS3), HA receptors and hyaluronidases (mainly HYAL1) are critical determinants of tumor growth and progression." (PMID 32610620, 2020). "HK2 gene was significantly and positively correlated with tumor size, whereas PFKFB3 was significantly and positively correlated with COL1A1, COL3A1, and HAS2 genes in TN." (PMID 31428701, 2019). "The novel finding that rhPRG4 opposes HAS2 and CD44 induction by TGFβ has implications for downregulating the tumor promoting roles, while maintaining the tumor suppressive aspects of TGFβ actions." (PMID 31361756, 2019).
tumor (continued). "We identified HAS2, tumor cell-derived HA and ZEB1 to form a positive feedback loop as ZEB1, elevated by HA, directly activates HAS2 expression." (PMID 28086235, 2017). "In invasive tumor stages RHAMM-, HAS1 and HAS2 mRNA-expression levels were elevated whereas HAS3v1 was reduced as compared to non-invasive tumors." (PMID 24069434, 2013). "IHC showed that the five markers, HYAL-1, HAS-2, N-Cadh, Slug, and MMP-9 included in the CM-6 signature, were upregulated in tumor tissues from patients who developed metastasis compared to normal colon tissues and in tumors from patients who did not develop metastasis." (PMID 40149256, 2025). "The inhibitory effect of 4-MU on HAS2/3, combined with its antitumor activity and effects on lipid metabolic pathways, provides a new potential direction for the treatment of HCC and the development of novel tumor therapeutic strategies." (PMID 40839202, 2025). "Importantly, our data indicate that bexarotene reduces LMWHA and HMWHA accumulation by suppressing the expression of HAS1, HAS3, and CEMIP in tumor cells and HAS1 and HAS2 in fibroblasts." (PMID 39858106, 2025). "It has to be highlighted that stromal cells play a pivotal role in producing abnormal amounts of HA, and in these cells, HAS1, and not HAS2, is the strongest isoform affecting tumor relapse and patient prognosis." (PMID 37568628, 2023). "MyCAFs were found to promote CCA tumor growth through hyaluronan synthase 2/hyaluronan (rather than type I collagen) mediated by the interactions with non-tumor cells and tumor cells." (PMID 36980203, 2023). "HAS2 improves cell viability, the capability to form tumour spheroids and has a negative prognostic value regarding overall survival." (PMID 35767191, 2022). "It is possible that an altered balance between HAS2 and HYAL1 upon UGT2B28 KD may contribute to the delay in tumor take and tumor growth, which would need to be verified in the future using additional experiments." (PMID 35954173, 2022). "Hyaluronic acid (HA), a major extracellular matrix proteoglycan that is synthesized mainly by hyaluronic acid synthase 2 (HAS2), combines with CD44s to activate the expression of ZEB1 in tumor cells, indicating that HAS2 and ZEB1 form a positive feedforward loop." (PMID 35454770, 2022). "Tumours have been proposed to produce very low molecular weight HA, which is specifically regulated by CAF due to the high expression of HAS2 and hyaluronidase (HYAL1) in CAF, which might contribute to greater production of HA in the CAF matrix." (PMID 34944493, 2021). "In this study, although the HA content did not exhibit a prognostic value, an association between tumor grade and HAS1, HAS2, and HYAL-2 was observed, and an increase in HAS2 was also correlated with a poor prognosis of the patients." (PMID 33744285, 2021). "Finally, in multiple breast cancerdatasets, high levels of ESRP1, ESRP1/HAS2, and ESRP1/ZEB1 correlate with poorprognosis, supporting the relevance of ZEB1/ESRP1 and ZEB1/HAS2 axes in tumorprogression." (PMID 31069317, 2018). "We show that HAS1, HAS2 and HYAL2 associate with tumor grade (WHO II-IV), and HAS2 is a negative prognostic factor in diffusely infiltrating astrocytomas." (PMID 29914429, 2018). "Thus, we propose that when FOXI3 in tumor cells modulate the secretion of other bone factors including SPOCK1, Dlx, MAF, PthrP, HAS2, SVEP1, TGFβ3, and FGF which further primes the microenvironment, creates a crosstalk to help tumors grow in the bone." (PMID 30018953, 2018). "Whereas the expression of HAS1 and HAS2 correlated with the content of hyaluronan in tumor tissue, and their expressions are not altered until the invasive phase of the disease, at which time hyaluronan content decreased." (PMID 27184066, 2016). "Similarly, forced expression of HAS3 promoted the tumorigenic ability of melanoma cells by accelerating tumor angiogenesis, but suppression of HAS2 or HAS3 inhibited the initiation and progression of primary and secondary tumor formation in vivo." (PMID 26322272, 2015).
tumor (continued). "Upregulation of HAS2 and MMP-13, in a similar fashion as TGFBI may imply their collective role in tumor progression." (PMID 25369402, 2014). "Of the stromal cells, 25–37% were HAS2 positive both in normal ovaries and in tumor specimens but the proportion of HAS2-positive stromal cells did not correlate either with HAS2 mRNA level, hyaluronan staining intensity or histological groups." (PMID 19435493, 2009). "While the stromal cells were positive for HAS2, their staining intensity did not correlate with that of stromal hyaluronan, nor with the tumor type or grade." (PMID 19435493, 2009). "In addition, HAS2/3 provides a favorable microenvironment for tumor cells by promoting their growth and metastasis through increased HA synthesis, and its activity is closely related to the extracellular matrix (ECM) in the tumor microenvironment." (PMID 40839202, 2025). "Some types of cancer cells express hyaluronan synthases (HAS1, HAS2, and HAS3), as well as fibroblasts and chondrocytes as part of the extracellular matrix, and the signaling between HA and CD44 is deemed critical for tumor proliferation and the spread of cancer." (PMID 40011711, 2025). "Similarly, HAS2 and HAS3 have also been shown to promote tumor growth and metastasis." (PMID 37110670, 2023). "In addition, HAS2 expression negatively correlated with amylo-α-1,6-glucosidase-4-α-glucanotransferase (AGL), one of the enzymes catalyzing glycogenolysis, which has been described as a tumor growth suppressor and prognostic marker in human BC." (PMID 37110670, 2023). "In addition, it could be researched more closely, if the possible connection between the expression of HAS2 and HYAL3 has a consequence for example for HA production or tumour cell behaviour." (PMID 35767191, 2022). "Not surprisingly, a number of proteins involved in tumor cell dissemination and BBB invasion were also found to associate with BCBM progression, including cathepsin-S, S100A4, RANKL, RANK, Src, HYAL1, HAS2 and prominin-1 (CD133)." (PMID 32110283, 2020). "Therefore, another possible explanation for the association of low HAS3 expression with a more favorable outcome may be that HAS3 is elevated in early tumor stages and HA synthesis is taken over by HAS1 and HAS2 during progression." (PMID 24069434, 2013). "However, in contrast to RHAMM the prognostic value of HAS2 was not independent from other strong prognostic factors such as lymph node invasion, histological grading and tumor stage." (PMID 24069434, 2013). "Thus, 4-MU may inhibit tumor progression by inhibiting FAS and HAS2/3." (PMID 40839202, 2025). "In addition, the relative importance of stromal versus tumour cell HAS expression has not been addressed experimentally in any cancer yet, which is due to the fact that HAS2 deficient mice are lethal and HAS1 and HAS3 deficient mice are not available to the scientific community." (PMID 21429221, 2011). "To our surprise, when we overexpressed HAS2 and HYAL1 in the luminal BC cell line MCF7, neither increased tumor cell adhesion, nor migration through the brain endothelium, nor any morphological alteration was observed." (PMID 36291142, 2022). "The hyaluronan synthase 2 myCAFs, but not type I collagen-expressing myCAFs, promoted tumor progression, while HGF-expressing iCAFs enhanced tumor growth via tumor-expressed MET, thereby directly linking CAFs to tumor cells." (PMID 35326670, 2022). "Interestingly, in our system, significantly increased expression of synthases (HAS2, HAS3) and hyaluronidases (HYAL1, HYAL3, HYAL4) was detected in the tumor cells but not in the stromal portion of TW2.6 tumors." (PMID 34869001, 2021). "When comparing TT and NAT, we noticed a high variability of HAS2, HAS3 and HYAL2 among the patients for both tumor types while HAS1 and HYAL3 could not be detected." (PMID 32610620, 2020).